WIPI1 (WD repeat domain, phosphoinositide interacting 1)
Description:
Component of the autophagy machinery that controls the major intracellular degradation process by which cytoplasmic materials are packaged into autophagosomes and delivered to lysosomes for degradation. Plays an important role in starvation- and calcium-mediated autophagy, as well as in mitophagy. Functions downstream of the ULK1 and PI3-kinases that produce phosphatidylinositol 3-phosphate (PtdIns3P) on membranes of the endoplasmic reticulum once activated. Binds phosphatidylinositol 3-phosphate (PtdIns3P), and maybe other phosphoinositides including PtdIns3,5P2 and PtdIns5P, and is recruited to phagophore assembly sites at the endoplasmic reticulum membranes. There, it assists WIPI2 in the recruitment of ATG12-ATG5-ATG16L1, a complex that directly controls the elongation of the nascent autophagosomal membrane. Together with WDR45/WIPI4, promotes ATG2 (ATG2A or ATG2B)-mediated lipid transfer by enhancing ATG2-association with phosphatidylinositol 3-monophosphate (PI3P)-containing membranes. Involved in xenophagy of Staphylococcus aureus. Invading S.aureus cells become entrapped in autophagosome-like WIPI1 positive vesicles targeted for lysosomal degradation. Also plays a distinct role in controlling the transcription of melanogenic enzymes and melanosome maturation, a process that is distinct from starvation-induced autophagy. May also regulate the trafficking of proteins involved in the mannose-6-phosphate receptor (MPR) recycling pathway.
Synonyms: WIPI49; FLJ10055; ATG18; ATG18A
Tractability: Antibody: UniProt places it where antibodies can reach, with medium confidence.
Gene: Protein-coding gene on chromosome 17 (68,420,948 to 68,457,520, reverse strand). Ensembl gene ENSG00000070540.
Subcellular location: Golgi apparatus, trans-Golgi network; Endosome; Cytoplasmic vesicle, clathrin-coated vesicle; Preautophagosomal structure membrane; Cytoplasm, cytoskeleton
Subcellular location (Human Protein Atlas): Golgi apparatus; Cytosol; Nucleoplasm
Pathways (Reactome):
Autophagy: Macroautophagy
Cellular responses to stimuli: XBP1(S) activates chaperone genes
Gene Ontology:
Molecular function: nuclear androgen receptor binding; nuclear estrogen receptor binding; phosphatidylinositol-3,5-bisphosphate binding; phosphatidylinositol-3-phosphate binding; protein binding; protein-macromolecule adaptor activity; signaling receptor binding
Biological process: autophagosome assembly; autophagy; cellular response to starvation; Golgi to endosome transport; positive regulation of autophagosome assembly; autophagy of mitochondrion; glycophagy; nucleophagy; pexophagy; protein localization to phagophore assembly site
Cellular component: autophagosome membrane; cytoplasm; endosome membrane; Golgi apparatus; phagophore assembly site; phagophore assembly site membrane; trans-Golgi network; cytosol; Golgi membrane; clathrin-coated vesicle; cytoskeleton; endosome
Genetic constraint (gnomAD): Loss-of-function variants: 42 observed, 51.39 expected, observed/expected ratio (o/e) 0.82, 90% interval 0.64 to 1.06. The upper end of that interval is the gene's LOEUF score, 1.06, which puts it in group 4 of 6, group 1 being the genes least tolerant of losing a copy. Missense variants: 419 observed, 539.99 expected, observed/expected ratio (o/e) 0.78, 90% interval 0.71 to 0.84. Synonymous variants: 185 observed, 210.2 expected, observed/expected ratio (o/e) 0.88, 90% interval 0.78 to 0.99.
Homologues: Orthologues: chimpanzee WIPI1 (99% identical), macaque WIPI1 (96% identical), guinea pig WIPI1 (95% identical), mouse Wipi1 (94% identical), dog WIPI1 (94% identical), rabbit WIPI1 (91% identical), pig WIPI1 (91% identical), rat Wipi1 (85% identical), tropical clawed frog wipi1 (75% identical), zebrafish wipi1 (70% identical), Drosophila melanogaster Atg18a (43% identical), Caenorhabditis elegans atg-18 (37% identical). Paralogues in human: WIPI2 (56% identical), WDR45 (23% identical), WDR45B (23% identical).
Diseases named in the same sentence as WIPI1 in open-access papers:
WIPI1 is named in the same sentence as 49 diseases in open-access papers, as found by Europe PMC text mining. Sharing a sentence is not in itself a finding about the gene and the disease. The quoted sentences say what the papers report.
melanoma (14 papers, 2017 to 2023). A malignant, usually aggressive tumor composed of atypical, neoplastic melanocytes. "WIPI1 is thought to be associated with osteosarcoma, nasopharyngeal carcinoma, melanoma, and other diseases." (PMID 36900050, 2023). "Noteworthily, BAG1, PEX3, and WIPI1 are all membrane-associated molecules and intracellular vesicles play a key role in melanoma biology." (PMID 30622661, 2018). "The molecular mechanisms underlying the functional interaction of BAG1, PEX3, and WIPI1 with melanoma were investigated with Chilibot analysis." (PMID 30622661, 2018). "That elevated WIPI1 levels are associated with improved survival is also indicated by the finding that elevated WIPI1 levels have prognostic survival value in human melanoma patients." (PMID 37620393, 2023). "The expression of WIPI1 is strongly elevated in human cancers such as melanoma and colon cancer, but the role of WIPI1 in the oncogenetic process of TNBC is unclear." (PMID 35186475, 2022). "Recently, three ARGs including WIPI1, BAG1 and PEX3 were found to be melanoma diagnostic biomarkers with high AUC values, sensibility and specificity values." (PMID 32003756, 2020). "WIPI1 has been proposed to be a new biomarker related to melanoma at both the gene and protein levels." (PMID 33126898, 2020). "WIPI1 expression shows a favorable prognostic value in melanoma, with very high statistical significance (p = 0.0003)." (PMID 30622661, 2018). "According to Pubmed searches, ARSA, the arylsulfatase A gene, appears to mediate BAG1, PEX3, and WIPI1 interaction with melanoma." (PMID 30622661, 2018). "In conclusion, the present study highlights 3 genes (BAG1, PEX3, and WIPI1), known to play a key role in autophagy, as novel relevant melanoma markers." (PMID 30622661, 2018). "A second-round validation performed on the Human Protein Atlas database showed strong differential protein expression for BAG1, PEX3, and WIPI1 in melanoma vs control samples, according to the image analysis of 80 human histological sections." (PMID 30622661, 2018). "WIPI1 gene expression also showed a significant prognostic value (p < 0.0001) according to 102 melanoma patients' survival data." (PMID 30622661, 2018). "BAG1, CHMP2B, PEX3, and WIPI1 confirm strongly different expression levels in melanoma vs healthy skin in IST Online." (PMID 30622661, 2018). "BAG1, PEX3, and WIPI1 were identified as the best three novel candidates as validated markers in both DNA and protein melanoma samples, while CHMP2B has validated differential expression at the DNA level, not observed at the protein level." (PMID 30622661, 2018). "Within more than 20 cancer types, the most relevant WIPI1 expression change (p = 0.00002; fold change = 3.1) was observed in melanoma." (PMID 30622661, 2018). "When such analysis was carried out on cancer cell lines, mostly melanoma cell lines show a significant and relevant change of WIPI1 (6 melanoma cell lines and 1 myeloma cell line)." (PMID 30622661, 2018). "Studies have reported that WIPI1 was highly expressed in both prostate cancer and melanoma." (PMID 34250091, 2021). "Additionally, WIPI1 was identified as the signature gene able to differentiate primary melanomas from normal skin." (PMID 30769764, 2019). "We concluded that the role of BAG1, PEX3, and WIPI1 as potential melanoma markers is novel and their action on melanoma may occur at the intracellular vesicle level via molecular pathways involving other ARGs." (PMID 30622661, 2018). "Interestingly, ARSA (arylsulfatase A) is the only ARG mediating BAG1, PEX3, and WIPI1 relation with melanoma." (PMID 30622661, 2018). "At the homepage of such database, by typing “WIPI1,” “Homo sapiens,” and “melanoma” in the search dialog windows, the Pan Cancer Analysis of Whole Genomes Project reports a clear increase of WIPI1 expression in melanoma vs normal skin (35 TPM vs “below cutoff,” respectively)." (PMID 30622661, 2018).
melanoma (continued). "Furthermore, WIPI1 was a relevant novel melanoma marker, and the increased expression of WIPI1 indicated poor clinical outcome in uveal melanoma In osteosarcoma, WIPI1 expression was obviously elevated, which promoted the proliferation of osteosarcoma cells through regulating CDKN1A expression." (PMID 34335109, 2021). "We finally addressed in Oncomine database whether WIPI1 overexpression is melanoma-specific." (PMID 30622661, 2018). "With regard to the genes specifically up-regulated in the MCSP CTC fraction, the majority have been involved in metastasis (LOXL4, ST6GALNAC2, PYGL), tumour growth (PLK2, CYSTM1, GLUL), and/or melanoma biology (SEC31A, WIPI1, SKP1)." (PMID 30769764, 2019). "We conclude that WIPI1 (AUC = 0.99), BAG1 (AUC = 1), and PEX3 (AUC = 0.93) are relevant novel melanoma markers at both gene and protein levels." (PMID 30622661, 2018). "WIPI1 is an ATG18 homolog; it colocalizes with the LC3 autophagy marker in melanoma cells and localizes within autophagosomes and endosomes." (PMID 30622661, 2018). "Interestingly, only WIPI1 and DDIT3 were shared between both CTC fractions and single melanoma cells." (PMID 30769764, 2019). "Similarly, the up-regulated genes in the ABCB5 CTC fractions were involved in metastasis (CALU, CYB5R1, DUSP3, CREG1, ENDOD1), tumour growth, and/or melanoma biology (H1F0, SCNA, WIPI1, TXN2)." (PMID 30769764, 2019). "We conclude that BAG1, CHMP2B, PEX3, and WIPI1 show a strongly different expression in melanoma vs control biopsies, according to data from 418 patients, and have never been related to melanoma according to Pubmed." (PMID 30622661, 2018). "However, DDIT3 was up-regulated as a result of the apoptotic activity triggered by the compound HA15 in melanoma cell lines, as was SEC31A, a gene found up-regulated in MCSP CTC fractions, Altogether, the role of WIPI1 and DDIT3 may indicate common molecular mechanisms in CTC biology." (PMID 30769764, 2019). "WIPI1 is significantly upregulated at both gene and protein levels in melanoma samples, showing the highest expression fold change, the highest ability to discriminate healthy individuals from patients, and the strongest prognostic value, and it has never been related to melanoma." (PMID 30622661, 2018).
osteosarcoma (5 papers, 2014 to 2023). A usually aggressive malignant bone-forming mesenchymal neoplasm, predominantly affecting adolescents and young adults. "have demonstrated that WIPI1 promotes osteosarcoma cell proliferation by inhibiting CDKN1A expression." (PMID 36185204, 2022). "Furthermore, WIPI1 is highly expressed in osteosarcoma cells and it promotes osteosarcoma cell proliferation." (PMID 36157071, 2022).
colon cancer (3 papers, 2016 to 2022). "Although the expression of these genes (with the exception of WIPI1) are higher in colon tumor and are related to poor prognosis, whether these genes influence the survival of patients with CC by regulating ferroptosis remains unknown." (PMID 33926457, 2021). "However, BIX01294 induced changes could be cell-type specific, as in human colon cancer HCT116 cells the expression of LC3B, ATG9A, ATG4A, but not ATG4B/C, ATG7, BECN1, WIPI1 was increased after BIX01294 treatment." (PMID 27934912, 2016).
glioma (3 papers, 2020 to 2022). A benign or malignant brain and spinal cord tumor that arises from glial cells (astrocytes, oligodendrocytes, ependymal cells). "We also found that WIPI1 knockdown can reverse the miR-450a-5p-induced effects on the proliferation, apoptosis, invasion, and migration of glioma cells." (PMID 32820249, 2020). "All these results indicate that WIPI1 knockdown can reverse the effects on proliferation, apoptosis, invasion, and migration induced by miR-450a-5p in glioma cells." (PMID 32820249, 2020). "The cell invasion and migration abilities of glioma cells were significantly promoted by WIPI1 knockdown when compared with the gefitinib and miR-450a-5p mimics group." (PMID 32820249, 2020). "We further confirmed that WIPI1 knockdown can negatively regulate the expressions of autophagy-related proteins and inhibit the formation of autophagosomes, which further indicated that miR-450a-5p can regulate the autophagy in glioma cells." (PMID 32820249, 2020). "On the basis of the important role of WIPI proteins in autophagy, our finding also demonstrated WIPI1 may also involve in the drug sensitivity of glioma cells to gefitinib." (PMID 32820249, 2020). "Therefore, we proposed that WIPI1 knockdown can reverse the effects induced by miR-450a-5p via blocking the progression of autophagy in glioma cells." (PMID 32820249, 2020).
anencephaly (2 papers, 2019 to 2020). A rare neural tube defect during pregnancy, resulting in the absence of a large portion of the brain and skull in the fetus. "Our findings suggest that functional variants in WIPI1 gene might contribute to the etiology of human anencephaly." (PMID 31849593, 2019). "This suggests that cases with anencephaly may be more likely to carry WIPI1 variants than cases with either spina bifida or encephalocele." (PMID 31849593, 2019). "Compared with East Asia WIPI1 variants in gnomAD database, there is significant (OR: 3.07, 95% CI: 1.07–8.84, Fisher’s exact test P-value: 0.053) enrichment of WIPI1 rare damaging missense variants in anencephaly." (PMID 31849593, 2019). "However, whole genome sequencing techniques found candidate NTDs loci and genes in chromosomes 2, 7, 10 and 17 (some of which, i.e. WIPI1, SPHKAP and NCOR1, have recently been associated with anencephaly)." (PMID 32448340, 2020). "Missense variants in WIPI1 may play a role in the genetic etiology of anencephaly, and LoF variants in SPHKAP and NCOR1 may also contribute to anencephaly." (PMID 31849593, 2019).
cholestasis (2 papers, 2018 to 2024). Impairment of the bile flow caused by obstruction within the liver, or outside the liver in the bile duct system. "DCF down-regulated many genes indicative of phospholipidosis, steatosis and cholestasis except for the ABCB1, which encodes for p-glycoprotein to aid in the elimination of xenobiotics, and WIPI1, which interacts with phospholipids." (PMID 30572671, 2018).
Sepsis (2 papers, 2023 to 2025). Sepsis is defined as life-threatening organ dysfunction caused by a dysregulated host response to infection. "The merged dataset (GSE57065 and GSE65682) revealed that all five genes (CD82, MAPK14, NEDD4, TXN, and WIPI1) were significantly upregulated in the sepsis group compared with the control group." (PMID 40299574, 2025). "The nomogram illustrates the individual contributions of the five genes (TXN, MAPK14, WIPI1, CD82, and NEDD4) and clinical information (age, gender) to the overall risk score, providing a practical tool for estimating the probability of sepsis." (PMID 40299574, 2025). "Consistent with our findings, in another bioinformatics study on ferroptosis-related genes, WIPI1 was found to be elevated in sepsis patients and correlated with patient outcomes." (PMID 37701780, 2023). "The four key genes that were identified to have both significant diagnostic and prognostic value in sepsis (IKBKB, PRKCQ, WIPI1, and SH3GLB1) were validated by RT-qPCR in whole blood samples obtained from sepsis patients and healthy controls." (PMID 37701780, 2023). "For example, TXN and MAPK14 are expressed predominantly in monocytes, whereas WIPI1, CD82, and NEDD4 exhibit variable expression in T and B cells, highlighting the diversity and composition of immune populations during sepsis." (PMID 40299574, 2025). "The results showed that IKBKB and PRKCQ were significantly downregulated in the sepsis group, while SH3GLB1 and WIPI1 were significantly upregulated." (PMID 37701780, 2023).
depression (1 paper, 2025). "WIPI1 (WD Repeat Domain, Phosphoinositide‐Interacting Protein 1) is involved in the regulation of autophagy and has been linked to depression." (PMID 41311024, 2025). "The role of WIPI1 in depression is an emerging area of research, with preliminary findings suggesting its potential involvement in the disorder's pathophysiology." (PMID 41311024, 2025). "In this study, the present findings reveals that the expressions of ULK1, MAPK14, WIPI1, and DUSP1 were associated with the immune system, thereby participated in the pathogenesis of depression and could provide potential targets for future treatments." (PMID 41311024, 2025).
heart failure (1 paper, 2020). Inability of the heart to pump blood at an adequate rate to meet tissue metabolic requirements. "Recent work examining tissue from the RV of human heart failure patients found a set of genes that are unique to RV failure compared to LV failure: WIPI1, HSPB6, SNAP47 and MAP4." (PMID 31960631, 2020).
major depressive disorder (1 paper, 2025). An episode of depression lasting two or more weeks without an intervening episode of mania. "This study explored ferroptosis involvement in major depressive disorder (MDD) by integrating GEO microarray data, WGCNA, and ferroptosis‐related gene analysis, identifying four key genes (MAPK14, WIPI1, DUSP1, ULK1) as diagnostic biomarkers." (PMID 41311024, 2025).
medullary carcinoma (1 paper, 2021). "In spontaneous medullary carcinoma in 7M rats, the expression level of Mapk8 was increased, and the expression levels of two other genes, Ulk1 and Wipi1, were decreased." (PMID 34580369, 2021). "In radiation-induced medullary carcinoma in 4W rats, the expression of Cdkn2a and Cxcr4 increased, whereas that of seven autophagy regulatory genes (Dapk1, Eif2ak3, Gaa, Hgs, Mapkl4, Mapt, and Pim2) and five autophagy machinery components (Atg4b, Atg5, Gabarapl2, Rab24, and Wipi1) decreased." (PMID 34580369, 2021).
metastatic melanoma (1 paper, 2018). A melanoma that has spread from its primary site to another anatomic site. "An additional way to evaluate the potential prognostic values of BAG1, PEX3, and WIPI1 was carried out by assessing their expression in primary vs metastatic melanoma samples." (PMID 30622661, 2018).
neural tube defect (1 paper, 2022). A congenital defect characterized by failure of the neural tube to close completely; this results in the presence of openings in the brain or spinal cord. "Whereas, there is no disease linked to WIPI1 yet, one study linked it neural tube defects (NTD)." (PMID 36157071, 2022).
ovarian carcinoma (1 paper, 2023). A malignant neoplasm originating from the surface ovarian epithelium. "Considering the comparable HR value of PINK1 and WIPI1, we used Kaplan–Meier Plotter database to further evaluate the association between PINK1 (or WIPI1) expression level and overall survival in patients with ovarian cancer." (PMID 37940999, 2023). "The results showed that the high expression level of PINK1 was significantly associated with the worse prognosis in ovarian cancer patients, while the WIPI1 expression level was not significant related to the poor prognosis." (PMID 37940999, 2023). "Nevertheless, the effect of WIPI1 could not be ruled out and it may play an important role in some particular histological types of ovarian cancer." (PMID 37940999, 2023).
type 2 diabetes (1 paper, 2022). "In agreement with our study, hepatic SCP2 expression was reduced in diabetic rat, WIPI1 expression were decreased in skeletal muscle from type 2 diabetes, decreased PRKAA1/AMPK phosphorylation was observed in high glucose-induced HK-2 cells." (PMID 35992146, 2022).
virus infection (1 paper, 2025). "WIPI1 and Beclin-1 expression increased after induction of autophagy by torin, but little change in expression was detected in SK-N-SH or IMR-32 cells following virus infection for 3 h at a high MOI." (PMID 40042894, 2025).